SNORD10 (small nucleolar RNA, C/D box 10)
Synonyms: mgU6-77
Gene: Small nucleolar RNA gene on chromosome 17 (7,576,811 to 7,576,952, forward strand). Ensembl gene ENSG00000238917.
Gene Ontology:
Biological process: RNA processing
Cellular component: nucleolus
Homologues: Orthologues: chimpanzee SNORD10 (100% identical), macaque SNORD10 (95% identical), pig SNORD10 (80% identical), rat Snord10 (78% identical), guinea pig SNORD10 (77% identical), mouse Gm25835 (76% identical), rabbit SNORD10 (70% identical).
Diseases named in the same sentence as SNORD10 in open-access papers:
SNORD10 is named in the same sentence as 8 diseases in open-access papers, as found by Europe PMC text mining. Sharing a sentence is not in itself a finding about the gene and the disease. The quoted sentences say what the papers report.
breast carcinoma (1 paper, 2024). "The results for those four snoRNAs suggest that they act as oncogenes, contrast with our results and suggest that, in breast cancer SNORA47, SNOR94, SNORA70 and SNORD10 may play a role as a tumor-suppressor gene (TSG) by yet unknown mechanisms." (PMID 38612790, 2024).
gastric tumors (1 paper, 2025). "Studies on gastric tumors have suggested potential roles for snoRNAs such as SNORA42, SNORA74A, and SNORD10 in gastric tumor pathogenesis." (PMID 40584410, 2025). "Studies on gastric tumors have suggested SNORA42, SNORA74A, and SNORD10 require further investigation to ascertain their potential as therapeutic targets." (PMID 40584410, 2025).
leiomyoma (1 paper, 2024). A well-circumscribed benign smooth muscle neoplasm characterized by the presence of spindle cells with cigar-shaped nuclei, interlacing fascicles, and a whorled pattern. "SNORA48 and SNORD10 (coding for small nucleolar RNAs) have not yet been described in leiomyomas, however were upregulated in both our cases." (PMID 37466765, 2024).
melanoma (1 paper, 2024). A malignant, usually aggressive tumor composed of atypical, neoplastic melanocytes. "In support of this argument, down-regulation of SNORD10 has been associated with epigenetic promoter silencing in stage IV melanoma cell lines." (PMID 38612790, 2024).
osteosarcoma (1 paper, 2024). A usually aggressive malignant bone-forming mesenchymal neoplasm, predominantly affecting adolescents and young adults.
cancer (1 paper, 2024). A tumor composed of atypical neoplastic, often pleomorphic cells that invade other tissues. "Among the DE sncRNAs in our list, four snoRNAs (SNORA47, SNORD94, SNORA70 and SNORD10) have been documented to be involved in various human cancers." (PMID 38612790, 2024).
tumor (1 paper, 2024). "Significant change of expression, reaching 10- to 58-fold change between uterine lesion compared to non-tumor counterpart, was observed in CAPN6, CD24, HMGA1, PLAG1, SNORA48, and SNORD10 (upregulation) and DKK3 and STK26 (downregulation)." (PMID 37466765, 2024).
SNORD10 also shares sentences with these, for which no sentence is quoted: gastric cancer (1 paper).